AGTPBP1 (ATP/GTP binding carboxypeptidase 1)
Description:
Metallocarboxypeptidase that mediates protein deglutamylation of tubulin and non-tubulin target proteins. Catalyzes the removal of polyglutamate side chains present on the gamma-carboxyl group of glutamate residues within the C-terminal tail of alpha- and beta-tubulin. Specifically cleaves tubulin long-side-chains, while it is not able to remove the branching point glutamate. Also catalyzes the removal of polyglutamate residues from the carboxy-terminus of alpha-tubulin as well as non-tubulin proteins such as MYLK. Involved in KLF4 deglutamylation which promotes KLF4 proteasome-mediated degradation, thereby negatively regulating cell pluripotency maintenance and embryogenesis.
Synonyms: CCP1; KIAA1035; NNA1; CONDCA
Tractability: Antibody: its Gene Ontology location is reachable by antibodies, with high confidence. PROTAC: ubiquitination databases record sites on it; its protein half-life has been measured.
Target class: Enzyme; Hydrolase
Gene: Protein-coding gene on chromosome 9 (85,546,539 to 85,742,144, reverse strand). Ensembl gene ENSG00000135049.
Subcellular location: Cytoplasm; Cytoplasm, cytosol; Nucleus; Mitochondrion
Subcellular location (Human Protein Atlas): Nucleoplasm; Basal body; Centriolar satellite; Plasma membrane; Primary cilium
Pathways (Reactome):
Metabolism of proteins: Carboxyterminal post-translational modifications of tubulin
Gene Ontology:
Molecular function: metallocarboxypeptidase activity; tubulin binding; zinc ion binding
Biological process: cerebellar Purkinje cell differentiation; eye photoreceptor cell differentiation; mitochondrion organization; neuromuscular process; olfactory bulb development; proteolysis
Cellular component: cytoplasm; nucleoplasm; nucleus; cytosol; microtubule cytoskeleton; mitochondrion
Genetic constraint (gnomAD): Loss-of-function variants: 49 observed, 111.82 expected, observed/expected ratio (o/e) 0.44, 90% interval 0.35 to 0.56. The upper end of that interval is the gene's LOEUF score, 0.56, which puts it in group 2 of 6, group 1 being the genes least tolerant of losing a copy. Missense variants: 1,075 observed, 1,331.1 expected, observed/expected ratio (o/e) 0.81, 90% interval 0.77 to 0.85. Synonymous variants: 407 observed, 461.43 expected, observed/expected ratio (o/e) 0.88, 90% interval 0.81 to 0.96.
Gene-disease validity (ClinGen):
ClinGen rates the evidence that AGTPBP1 causes each of these diseases.
neurodegeneration, childhood-onset, with cerebellar atrophy (autosomal recessive): Definitive. An autosomal recessive disorder characterized by early onset of progressive neurodegeneration affecting the central and peripheral nervous systems.
Homologues: Orthologues: macaque AGTPBP1 (99% identical), chimpanzee AGTPBP1 (99% identical), dog AGTPBP1 (95% identical), pig AGTPBP1 (94% identical), rabbit AGTPBP1 (92% identical), mouse Agtpbp1 (90% identical), rat Agtpbp1 (89% identical), guinea pig AGTPBP1 (85% identical), tropical clawed frog agtpbp1 (73% identical), zebrafish agtpbp1 (61% identical). Paralogues in human: AGBL1 (42% identical), AGBL2 (19% identical), AGBL3 (19% identical), AGBL4 (13% identical), AGBL5 (12% identical).
Diseases named in the same sentence as AGTPBP1 in open-access papers:
AGTPBP1 is named in the same sentence as 31 diseases in open-access papers, as found by Europe PMC text mining. Sharing a sentence is not in itself a finding about the gene and the disease. The quoted sentences say what the papers report.
male infertility (4 papers, 2017 to 2026). The inability of the male to effect fertilization of an ovum after a specified period of unprotected intercourse. "The study contributes to our understanding of the molecular mechanisms underlying teratozoospermia and male infertility as a result of the R811H mutation in the AGTPBP1 gene." (PMID 41160201, 2026). "The Agtpbp1 allele deletion is identified in the spontaneous recessive pcd mouse strain, which exhibits Purkinje cell degeneration and male infertility." (PMID 41160201, 2026). "This study identifies the role of AGTPBP1 mutations in teratozoospermia and provides potential guidance for the diagnosis and treatment of male infertility." (PMID 37937809, 2024). "Furthermore, deletion of the Agtpbp1 allele in spontaneous strain mice not only causes neuronal degeneration but also results in male infertility." (PMID 37937809, 2024). "Notably, the sperm head and tail phenotypes observed in Agtpbp1‐defective mice resembled those observed in patients carrying AGTPBP1 missense mutations, providing strong evidence that AGTPBP1 is a human male infertility gene." (PMID 37937809, 2024). "Five of these genes were characterized as male infertility‐related genes, including Polo‐like kinase 4 (PLK4), AGTPBP1, KISS1 receptor, Meiosis Expressed Gene 1 (MEIG1), and Piwi Like RNA‐Mediated Gene Silencing 2 (PIWIL2)." (PMID 37937809, 2024).
Ataxia (3 papers, 2021 to 2023). Ataxia refers to impaired coordination of voluntary muscle movement. "In particular, in the Purkinje cell degeneration (pcd) mouse model, mutations in AGTPBP1 lead to early cerebellar ataxia, which correlates with the massive loss of cerebellar Purkinje cells." (PMID 34572343, 2021).
Cerebellar atrophy (2 papers, 2011 to 2021). Cerebellar atrophy is defined as a cerebellum with initially normal structures, in a posterior fossa with normal size, which displays enlarged fissures (interfolial spaces) in comparison to the foliae secondary to loss of tissue. "Shashi and colleagues (2018) identified biallelic variants in the AGTPBP1 gene in patients suffering from an infantile-onset neurodevelopmental disorder known as childhood-onset neurodegeneration with cerebellar atrophy (CONDCA)." (PMID 34572343, 2021). "Recent reports have identified rare, biallelic damaging variants of the AGTPBP1 gene that cause a novel and documented human disease known as childhood-onset neurodegeneration with cerebellar atrophy (CONDCA), linking loss of function of the AGTPBP1 protein to human neurodegenerative diseases." (PMID 34572343, 2021). "Further analysis is needed to examine whether only AGTPBP1 mutations affecting the catalytic domains of the protein are directly associated with cerebellar atrophy." (PMID 34572343, 2021). "A large battery of motor tests were used to evaluate the degree of cerebellar atrophy and the consequent impairment of locomotor coordination, as well as progressive weakness of musculature and cognitive decline in AGTPBP1-depleted mice." (PMID 34572343, 2021). "It is relevant to mention that in a very recently published paper, two members of a consanguineous family harbouring a novel homozygous variant (c.3293G>A) at the 3′ end of the AGTPBP1 gene showed no signs of cerebellar atrophy." (PMID 34572343, 2021).
colorectal cancer (2 papers, 2009 to 2020). A primary or metastatic malignant neoplasm that affects the colon or rectum. "Our study showed that genes co-expressed with AGTPBP1 were associated with Nef genes of human immunodeficiency virus (HIV) and signal transduction, which antagonize the chemokine receptor CXCR4 and have an apoptotic effect on human colorectal cancer." (PMID 33276627, 2020).
lung carcinoma (2 papers, 2020 to 2024). "To identify the alteration frequency of AGTPBP1 gene in LUAD, we analyzed mutations and CNAs of AGTPBP1 in a cohort of 4268 patients with lung cancer using the cBioPortal web." (PMID 33276627, 2020). "A total of 38 mutations in the AGTPBP1 gene were identified among lung cancer samples; the mutations were evenly distributed in all regions, including zinc carboxypeptidase, which belongs to the M14 peptidase family with 874–1107 amino acids." (PMID 33276627, 2020). "The association between AGTPBP1 expression and the survival of patients with lung cancer was examined using R2: Genomics Analysis and Visualization Platform, KM-plotter, and PrognoScan database." (PMID 33276627, 2020). "We further evaluated the association of AGTPBP1 with immune cell infiltration and cytotoxicity markers in lung cancer using the TIMER webtool." (PMID 33276627, 2020). "In this study, we provided evidence for the potential function of AGTPBP1 and its clinical association with lung cancer." (PMID 33276627, 2020). "In this study, we examined the role of AGTPBP1 in cancer progression, its association with patient survival, and related mechanisms in lung cancer, using the A549 cell line and lung cancer gene expression datasets." (PMID 33276627, 2020). "Association of lower AGTPBP1 expression with poor prognosis suggested a diagnostic value of AGTPBP1 in lung cancer." (PMID 33276627, 2020). "The prognostic value of AGTPBP1 and its associated pathways in lung cancer were investigated by analyzing the publicly accessible lung cancer datasets." (PMID 33276627, 2020). "Furthermore, we investigated the possible pathways associated with AGTPBP1 in lung cancer by analyzing the genes co-expressed with AGTPBP1 using five different datasets." (PMID 33276627, 2020). "Altogether, our findings indicated that the low expression of AGTPBP1 was associated with high ER stress in tumors, which might be related to poor outcomes in patients with lung cancer." (PMID 33276627, 2020). "CCP1, encoded by AGTPBP1, mediates the deglutamylation of tubulin, which could influence tubulin dynamics and the microtubule network in lung cancer." (PMID 33276627, 2020). "In addition, in vivo studies must be carried out in the future to clearly understand the mechanisms underlying the role of AGTPBP1 in lung cancer." (PMID 33276627, 2020). "Overall, these results suggested that alteration of AGTPBP1 could be associated with lung cancer." (PMID 33276627, 2020). "We also analyzed the relationship between AGTPBP1 expression and patient survival rate in various lung cancer datasets using web-based analysis tools, including KM-plotter and PrognoScan." (PMID 33276627, 2020). "Our results indicated that AGTPBP1 expression in lung cancer tissues was lower than in normal counterparts and positively correlated with overall patient survival in lung cancer." (PMID 33276627, 2020). "In this study, we examined the effect of AGTPBP1 on the proliferation, migration, and cancer stemness of lung cancer cells in vitro by silencing AGTPBP1 with short-hairpin RNA (shRNA)." (PMID 33276627, 2020). "Co-occurrence of mutation in AGTPBP1 and other altered biomarkers EGFR, KRAS, BRAF, ALK and ROS1 in lung cancer was analyzed." (PMID 33276627, 2020). "We found that reduced AGTPBP1 expression by knockdown in lung cancer cells increased the oncogenic characteristics, including proliferation, migration, sphere formation, and drug resistance, of cells in vitro." (PMID 33276627, 2020). "To assess the role of AGTPBP1 in lung cancer cell, we interfered AGTPBP1 expression in A549 cells using AGTPBP1-targeted shRNA." (PMID 33276627, 2020). "CNA analysis showed that a significant proportion of the lung cancer tissues displayed shallow deletion, and AGTPBP1 expression was significantly reduced in cells with shallow deletion as compared to diploid cells." (PMID 33276627, 2020).
lung carcinoma (continued). "Our results conclusively suggested that AGTPBP1 expression was correlated with cancer progression and immune infiltration in lung cancer." (PMID 33276627, 2020). "Analysis of co-expressed genes revealed that AGTPBP1 expression positively correlated with immune infiltration in lung cancer." (PMID 33276627, 2020). "To investigate the correlation between the mRNA level of AGTPBP1 and the clinicopathological characteristics of lung cancers, we analyzed TCGA datasets using the UALCAN tool." (PMID 33276627, 2020). "Lung cancer datasets revealed significantly lower mRNA and protein expression levels of AGTPBP1 in lung cancer tissues, as compared to those in normal tissues." (PMID 33276627, 2020). "Our systematic analysis reveals the prognostic value of AGTPBP1 expression and suggests potential AGTPBP1-related mechanisms in lung cancer progression, which include the effects on oncogenic properties in tumor cells and tumor immune microenvironments." (PMID 33276627, 2020). "Altogether, these results indicated that the mRNA and protein expression levels of AGTPBP1 were lower in lung cancer tissues, as compared to its neighboring normal tissues." (PMID 33276627, 2020). "AGTPBP1 expression also correlated with immune infiltration in lung cancer." (PMID 33276627, 2020). "Therefore, we analyzed the relationship between AGTPBP1 expression and prognosis in lung cancer using gene expression datasets." (PMID 33276627, 2020). "To elucidate the potential signaling mechanism related to AGTPBP1 expression in lung cancer, we acquired the correlation gene sets from the following five different transcriptome datasets of lung cancer using the R2 data tool: GSE63074, GSE19804, GSE33532, GSE19188, and LUAD-TCGA." (PMID 33276627, 2020). "Therefore, our study revealed the role of AGTPBP1 in lung cancer and its prognostic significance in patient survival." (PMID 33276627, 2020). "Thus, investigation of the AGTPBP1 functions is required for a better understanding in tubulin homeostasis in lung cancer." (PMID 33276627, 2020). "In this multidimensional analysis of AGTPBP1 expression in lung cancer database and in vitro with a cancer cell line, we suggested the first evidence of the correlation between the AGTPBP1 expression and clinical outcomes in lung cancer." (PMID 33276627, 2020). "Thus, our study contributes an overall understanding of the therapeutic role of AGTPBP1 in lung cancer and the possible therapeutic use for the cure of lung cancer patients." (PMID 33276627, 2020). "In both datasets, mRNA expression of AGTPBP1 was significantly downregulated in lung carcinomas." (PMID 33276627, 2020). "A differential effect of AGTPBP1 expression on the genetical subtypes of lung cancer could be investigated using additional lung cancer cell lines without KRAS mutation such as HCC78 and EBC-1 in future study." (PMID 33276627, 2020). "Our results suggested that lower expressions of AGTPBP1 were associated with low cytotoxicity in LUAD, and AGTPBP1 might be a prognostic factor for lung cancer." (PMID 33276627, 2020). "Moreover, AGTPBP1 expression was downregulated in lung cancer tissues, as compared to their adjacent normal lung tissues in NSCLC." (PMID 33276627, 2020). "Overall, knockdown of AGTPBP1 enhanced the oncogenic characteristics, including proliferation, migration, self-renewal, and drug-resistance, of A549 lung cancer cells, suggesting that AGTPBP1 had a tumor-suppressing ability and could modulate the progression of LUAD." (PMID 33276627, 2020). "Therefore, modulation of AGTPBP1 expression could be a potential therapeutic approach for lung cancer." (PMID 33276627, 2020). "Additionally, AGTPBP1 is known to play an essential role in T lymphocyte development in zebrafish, suggesting the important role of AGTPBP1 in the control of the tumor immune microenvironment in lung cancer." (PMID 33276627, 2020).
lung carcinoma (continued). "Moreover, we observed that 3 out of 12 lung cancer tissues, including that of patient ID 447, showed a low level of staining for AGTPBP1, whereas immunohistochemistry data from HPA showed moderate cytosolic staining for AGTPBP1 in normal lung tissues." (PMID 33276627, 2020).
non-small cell lung carcinoma (2 papers, 2020 to 2024). A group of at least three distinct histological types of lung cancer, including non-small cell squamous cell carcinoma, adenocarcinoma, and large cell carcinoma. "Although its dysregulated expression has been linked to the development of non-small cell lung cancer, the specific roles and mechanisms of AGTPBP1 in pancreatic cancer (PC) have yet to be fully understood." (PMID 39129004, 2024). "The expression of AGTPBP1 in non-small cell lung cancer (NSCL) was correlated with cancer progression and immune invasion by bioinformatics analysis, suggesting that this gene may be closely related to tumor progression." (PMID 39129004, 2024).
Obesity (2 papers, 2018 to 2025). Accumulation of substantial excess body fat. "The SNP rs7863248 in AGTPBP1 was also associated with the prevalence of obesity in the replication study." (PMID 29341862, 2018). "rs7863248 of AGTPBP1 was significantly associated with BMI in women in the discovery cohort, whereas this SNP was related to BMI in men and all individuals and the prevalence of obesity in the replication cohort." (PMID 29341862, 2018). "Furthermore, the SNP rs7863248 in AGTPBP1 correlates with obesity prevalence in humans." (PMID 40650015, 2025).
teratozoospermia (2 papers, 2024 to 2026). "In our previous study, we identified three AGTPBP1 mutations (p.Glu423Asp, p.Pro631Leu, and p.Arg811His) in teratozoospermia cases." (PMID 41160201, 2026). "The present study is the first to establish a connection between the genetic mutations in AGTPBP1 to teratozoospermia." (PMID 37937809, 2024). "We suggest that mutated AGTPBP1 may be involved in human teratozoospermia." (PMID 37937809, 2024). "In our previous study, Arg-to-His substitution at position 811 of AGTPBP1 in teratozoospermia cases resulted in AGTPBP1 protein instability and mislocalization." (PMID 41160201, 2026). "In this study, three sporadic genetic alterations in AGTPBP1 in Taiwanese patients with teratozoospermia were identified using WES." (PMID 37937809, 2024). "In this study, we established a link between genetic changes in AGTPBP1 and human teratozoospermia for the first time and identified the role of AGTPBP1 in deglutamination, which is crucial for sperm formation." (PMID 37937809, 2024). "In the present study, we identified three genetic alterations in AGTPBP1 in patients with teratozoospermia (affected individual A: p.Glu423Asp and p.Pro653Leu; affected individual B: p.Arg811His)." (PMID 37937809, 2024). "In this study, we screened patients with teratozoospermia in Taiwan for genetic alterations using whole‐exon sequencing (WES) and identified three genetic mutations in AGTPBP1." (PMID 37937809, 2024). "Further investigation is required to understand the genetic changes in AGTPBP1 that lead to CONDCA and teratozoospermia." (PMID 37937809, 2024).
Alzheimer disease (1 paper, 2024). A progressive, neurodegenerative disease characterized by loss of function and death of nerve cells in several areas of the brain leading to loss of cognitive function such as memory and language. "Interestingly, several transcriptome-wide significant and colocalized genes outside genome-wide significant GWAS loci point to biologically relevant pathways related to neurodevelopment and neurodegeneration (PICALM, a known Alzheimer disease gene, CAMSAP2, AGTPBP1, SETD1A, EPRS, PADI2 and PSAP)." (PMID 38811690, 2024).
amyotrophic lateral sclerosis (1 paper, 2021). Amyotrophic lateral sclerosis (ALS) is a neurodegenerative disease characterized by progressive muscular paralysis reflecting degeneration of motor neurons in the primary motor cortex, corticospinal tracts, brainstem and spinal cord. "Interestingly, a recent study has identified the AGTPBP1 gene as being the most significant gene coexpressed with the amyotrophic lateral sclerosis (ALS)-linked gene C90RF72 and revealed a positive correlation between the expression of their respective mRNAs." (PMID 34572343, 2021).
erythroderma (1 paper, 2021). "The patient’s clinical manifestations included novel phenotypes such as erythroderma and an abnormal metabolic profile, which have not been reported before in patients with recessive mutations in AGTPBP1." (PMID 34324503, 2021).
infertile (1 paper, 2026). "Three AGTPBP1 non-synonymous mutations (E423D, P631L, and R811H) in infertile cases displaying sperm morphological defects were identified." (PMID 41160201, 2026). "Sperm from the Agtpbp1R791H/R791H knock-in mice exhibited morphological changes at a lesser frequency in comparison to the mice lacking the entire carboxypeptidase A domain of AGTPBP1 or infertile men carrying the R811H mutation." (PMID 41160201, 2026).